H19 (H19 imprinted maternally expressed transcript)
Diseases named in the same sentence as H19 in open-access papers (continued):
Sharing a sentence is not in itself a finding about the gene and the disease.
infection (14 papers, 2009 to 2025). The state of being infected such as from the introduction of a foreign agent such as serum, vaccine, antigenic substance or organism. "Given that the AAV used in this experiment causes widespread infection of brain tissue 14 days after injection and lacks cellular specificity, it is impossible to determine the effect of H19‐KD on a single cell type." (PMID 39049714, 2024). "Further analysis showed that H19 knockdown alleviated GZ7/cagA infection-induced S phase arrest and facilitated cell entry into the G2 phase, thereby improving cell cycle progression." (PMID 38902391, 2024). "Briefly, MSCs (C3H10T1/2) infected with adenovirus expression H19 were cultured in micromass; 3 days after infection, cells were lysed and mixed with anti-Runx2 tagged beads." (PMID 32903671, 2020). "The chondrogenic differentiation‐promoting effect of H19 overexpression was negated when miR‐29b‐3p expression was up‐regulated by Lenti‐miR‐29b‐3p infection." (PMID 33058414, 2020). "Alcian blue staining revealed that Lenti‐miR‐29b‐3p infection reduced production of proteoglycan in the differentiated cells and attenuated the H19 overexpression‐mediated promotion of proteoglycan content." (PMID 33058414, 2020). "After infection with ad-H19, RT-qPCR analysis indicated that H19 expression significantly increased in differentiated primary satellite cells." (PMID 33115498, 2020). "Conversely, silencing endogenous H19 inhibited and/or prevented the expression of these genes at 36 or 72 hours after Ad‐siH19 infection, except that Pras40 and Mtor were up‐regulated at 72 hours." (PMID 31809000, 2020). "In contrast, YWHAZ expression was upregulated in H19 knockdown cells, and GZ7/cagA infection could respond to the high YWHAZ expression caused by H19 knockdown." (PMID 38902391, 2024). "GZ7/cagA infection responded to the increased YWHAZ expression induced by H19 knockdown." (PMID 38902391, 2024). "Interestingly, the upregulation of H19 was more pronounced in the GZ7/cagA infection group compared to the GZ7/ΔcagA infection group." (PMID 38902391, 2024). "Interestingly, GZ7/cagA infection counteracted the upregulation of YWHAZ expression induced by si-H19." (PMID 38902391, 2024). "Overexpression of lncRNA H19 was confirmed by qRT-PCR on day 3 after infection." (PMID 35249446, 2022). "Infection of ecESCs from 4 patients with LV-H19-shRNA led to decreased lncRNA H19 expression." (PMID 33656053, 2021). "Furthermore, the up‐regulation of protein levels of SOX9, collagen II and aggrecan in the H19‐overexpressing cells was rescued following Lenti‐miR‐29b‐3p infection." (PMID 33058414, 2020). "When inflammation ends, H19 overexpression upregulated the TJ proteins to restore the blood-milk barrier, which has a great significance for the recovery of mammary gland function after infection." (PMID 30984483, 2019). "To examine how manipulating H19 expression affects brain injury and neurological function recovery after TBI, we constructed an adeno‐associated virus vector AAV9‐shRNA‐H19, injected into the right lateral ventricle of mice 14 days before TBI, ensuring ample time for infection and shRNA expression." (PMID 39049714, 2024). "In the present study, lncRNA H19 was highly expressed in the middle and late stages of infection, which suggests that it may play a role in regulating cell proliferation, apoptosis, and immunity induced by A. cantonensis infection, which needs to be further investigated." (PMID 38715092, 2024). "Similar to H19 overexpression though, silencing H19 expression also up‐regulated most of the genes involved in lipid breakdown, such as Acat2, Cpt1b, Ndafs4, Pck2, Cyp1a2, Acads and Atpsa1, at 72 hours after Ad‐H19 infection, although most of them were down‐regulated at 36 hours after infection." (PMID 31809000, 2020). "The results showed that GZ7/cagA infection decreased YWHAZ expression, which is consistent with the observed reduction in YWHAZ expression in cells overexpressing H19." (PMID 38902391, 2024).
infection (continued). "We found that Ad‐H19‐mediated H19 overexpression in hepatocytes increased MLXIPL expression at 3 and 5 days after infection, while silencing H19 significantly inhibited MLXIPL expression in hepatocytes at protein level." (PMID 31809000, 2020). "After infecting early passage DP cells (DP3) with recombinant lentiviruses, QPCR showed a significantly upregulated level of H19, and GFP fluorescence, indicating high infection efficiency." (PMID 32849769, 2020). "Furthermore, qPCR analysis revealed that H19 overexpression in hepatocytes led to the increased expression of numerous genes involved in lipid synthesis and storage, such as Gpam, Mogat, Fasn, Acaca, Apoc3, Srebp, Plin2, Plin3, Lipe and Mlxipl at 72 hours after Ad‐H19 infection." (PMID 31809000, 2020). "We next compared the methylation pattern of the same H19 IRC, including that 6th CTCF binding site, among all four hMSC populations twelve days following infection with SYT-SSX1-containing retrovirus or an empty vector." (PMID 19936258, 2009). "Furthermore, FISH analysis revealed a significant increase in H19 localisation in the cytoplasm after infection with GZ7/ΔcagA and GZ7/cagA strains compared to the control group with H19 being more abundant in the cytoplasm of GZ7/cagA infected cells." (PMID 38902391, 2024). "Interestingly, H19 knockdown effectively reduced cell proliferation, invasion, and migration generated by GZ7/ΔcagA and GZ7/cagA infection." (PMID 38902391, 2024). "In addition, H19 knockdown stimulated cells to enter the G2-phase and attenuated the effect of GZ7/cagA infection on the cellular S-phase barrier." (PMID 38902391, 2024). "RTCA assay of cell proliferation showed that si-H19 transfection significantly decreased the proliferation ability of cells compared to the normal control group, and H19 knockdown significantly inhibited cell proliferation induced by GZ7/ΔcagA and GZ7/cagA infection." (PMID 38902391, 2024). "In addition, we found H19 overexpression inhibited the adhesion of S. aureus into MAC-T, which could protect mammary gland alveoli from further infection of pathogens." (PMID 30984483, 2019).
metabolic disorders (12 papers, 2021 to 2025). "A similar conclusion was drawn from the analysis of fatty acid biosynthesis-related genes, suggesting that H19 inhibition stabilizes the metabolic disorders induced by OGD/R." (PMID 40076761, 2025). "Moreover, there might be an association between H19 and cardiovascular and metabolic diseases." (PMID 37189829, 2023). "The expression level of fasting plasma glucose (FPG), a sensitive indicator in the early stage of metabolic disease, is positively correlated with H19 in PCOS patients." (PMID 35103065, 2022). "Collectively, these findings suggest that DNA methylation-mediated the downregulation of H19 expression plays a crucial role in cardiomyocyte or H9c2 cells metabolic disorders and induces cardiac respiratory dysfunction by promoting mitophagy." (PMID 34050133, 2021). "The effects of H19 on metabolic disorders, mitochondrial respiratory function, and mitophagy were investigated." (PMID 34050133, 2021). "Altogether, these results suggest that NIC could alter the expression levels of H19 through dysregulation of the DNA methylation status, with possible clinical implications correlated with perturbation of fetal growth and metabolic disorders in adulthood." (PMID 38867535, 2024).
heart disease (10 papers, 2016 to 2025). "Through these databases, the association of DE lncRNAs with heart disease was detected, especially the H19 and FTX genes were mentioned in both databases." (PMID 35415316, 2022). "Moreover, aberrantly expressed H19 is associated with various heart diseases and is suitable for use as a biomarker for CH." (PMID 35139769, 2022). "Cardiac disease in adults is dependent only on loss of H19 lncRNA expression." (PMID 34402430, 2021). "As far as current research is concerned, H19 can positively or negatively regulate apoptosis, which may provide valuable insights for understanding the pathogenic role of H19 in the development of heart disease." (PMID 34344446, 2021). "The divergent regulation of H19 between pediatric and adult failing hearts emphasizes the need to consider developmental stage when evaluating lncRNA-mediated mechanisms in heart disease." (PMID 41446187, 2025). "Bioinformatics analysis showed that miR-145-3p was a target of H19, since miR-145-3p participated broadly in heart diseases." (PMID 35139769, 2022). "Both lncRNA databases manifested the role of H19, one of the 16 overlapping DE lncRNAs, in several heart diseases." (PMID 35415316, 2022). "All these studies show that H19 plays a crucial role in the occurrence and development of heart disease and will become a new hot spot and focus of cardiovascular basic and clinical research." (PMID 34344446, 2021). "This network highlights some key lncRNAs, such as H19 and BDNF-AS, which strongly connect to cardiac diseases." (PMID 35415316, 2022). "Downregulation of H19 promoted cell proliferation and inhibited cell apoptosis during late-stage cardiac differentiation by regulating the negative role of miR-19b in Sox6 expression, which suggested that the manipulation of H19 expression could serve as a potential strategy for heart disease." (PMID 27895893, 2016). "Another study emphasized the important function of other lncRNAs such as H19, MALAT1, and MDNCR at different stages of human cardiac development and heart disease, which inform the lncRNAs’ abilities becoming potential biomarkers as well as therapeutic targets in heart diseases." (PMID 35415316, 2022).
gastrointestinal tumors (6 papers, 2016 to 2022). "The H19 rs2839698 polymorphism effects were tissue-specific, which may give a clue for early screening of the digestive system tumor." (PMID 36588790, 2022). "We additionally performed a disease-specific meta-analysis on digestive tumors, and the results indicated a significant association between HCC and GC as well as H19 rs2839698 than CRC." (PMID 36588790, 2022). "A recent study also showed that cholangiocyte-derived H19-exosomes were involved in macrophage activation and hepatic inflammation in cholestatic liver injury." (PMID 34168124, 2021). "H19 deficient mice represented attenuated liver damage and fibrosis compared to wild-type mice after BDL, indicating the association of expression levels of H19 and liver conditions during cholestatic liver injury." (PMID 32154257, 2020). "Long noncoding RNA (lncRNA) H19 has been reported to be upregulated in malignant digestive tumors, but its clinical relevance is not yet established." (PMID 27738631, 2016).
adenocarcinoma (5 papers, 2015 to 2021). A common cancer characterized by the presence of malignant glandular cells. "ROC curve analysis established the optimal cut-off value 1.178 of H19 expression level in 136 adenocarcinoma tissues, which yielded an area under the curve (AUC) of 0.751 (P < 0.01)." (PMID 27911863, 2017). "Therefore, the growing expression H19 level in adenocarcinoma cells would respond to cisplatin treatment." (PMID 27911863, 2017).
neurological diseases (5 papers, 2020 to 2025). "Numerous studies have highlighted the role of H19 in regulating microglia/macrophage activation across different neurological diseases, impacting the inflammatory response." (PMID 39049714, 2024). "LncRNA H19 has been reported to regulate apoptosis and neurological diseases." (PMID 36364766, 2022). "It was potential that lncRNA H19 acted as a well-equipped biomarker in neurological diseases." (PMID 33708438, 2021). "In the aggregate, lncRNA H19 expression was positive in neurological diseases, such as SCI." (PMID 33708438, 2021). "Accumulating evidence has elucidated that lncRNAs could change some biological progress through the modulation of miRNAs in neurological diseases, such as lncRNA H19." (PMID 33708438, 2021). "Moreover, the role of lncRNA H19 in a large amount of neurological diseases has also been expounded." (PMID 33708438, 2021). "Since miR-301b-3p expression is up-regulated in neurologic disorders, we selected miR-301b-3p as the research biomarker, to test the hypothesis that H19 might regulate HPRT1 expression by “sponging” miR-301b-3p, thus participating in the 6-OHDA-induced dopaminergic neuron loss." (PMID 32434961, 2020).
renal disease (5 papers, 2016 to 2023). "In addition, in patients with renal disease, HHcy led to a shift from monoallelic to biallelic expression of H19, and in CBS-deficient mice, the expression of H19 was also significantly increased." (PMID 30781581, 2019). "We also investigated the expression pattern of miR-17 and H19 in advanced kidney disease induced by adenine." (PMID 27391349, 2016). "The lncRNA H19 is the first imprinted gene, which is expressed in the embryo and down-regulated at birth, and its role in tumors has long been a subject of controversy, however, in recent years, it has received increasing attention in kidney disease." (PMID 37964955, 2023). "This study indicates that H19 upregulation contributes to kidney fibrosis, and that H19 inhibition may represent novel anti-fibrotic treatment in renal diseases." (PMID 32295041, 2020). "H19 inhibition might represent a novel anti-fibrotic treatment in renal diseases." (PMID 27391349, 2016). "Antagonism of H19 may represent a novel anti-fibrotic treatment in renal diseases." (PMID 27391349, 2016). "However, the role of H19 in renal diseases still remains unclear." (PMID 27391349, 2016). "In addition, it is noteworthy that by analyzing lncRNA studies performed on renal diseases, we can identify six lncRNAs involved in more than one type of renal disease, in particular PVT1, TUG1, NEAT1, MALAT1, XIST, and H19." (PMID 37190024, 2023).
digestive system cancer (4 papers, 2016 to 2025). A primary or metastatic malignant neoplasm involving any part of the digestive system. "In summary, an increasing number of studies have investigated the role of H19 in conferring drug resistance of digestive system cancers and explored the underlying mechanisms." (PMID 33402118, 2021). "Future studies are required for in-depth characterization of the involvement of H19 in mediating therapy resistance of digestive system cancer and its underlying mechanisms." (PMID 33402118, 2021). "The current meta-analysis was to investigate the association between lncRNA H19 expression and pathological features in digestive system cancers." (PMID 27738631, 2016). "The meta-analysis was to investigate the association between H19 expression and pathological features of digestive system cancers." (PMID 27738631, 2016). "In this review, we discuss the potential mechanisms of LncRNA H19 related therapy resistance in the context of digestive system cancers." (PMID 33402118, 2021). "In this article, we focus exclusively on the molecular mechanism of therapeutic resistance in the context of digestive system cancers and highlight the potential contribution of H19 to the development of resistance to chemotherapy and radiotherapy." (PMID 33402118, 2021). "Therefore, the high expression of lncRNA H19 might predict poor oncological outcomes of patients with digestive system cancers." (PMID 27738631, 2016). "The recent studies have indicated that overexpression of H19 also promoted EMT progression in EC, GC, GBC, and CRC in vitro, which suggested that lncRNA H19 might play an important role in invasiveness and metastasis, as a biomarker for prognosis of digestive system cancers." (PMID 27738631, 2016).
psychiatric disorder (4 papers, 2015 to 2024). A disorder characterized by behavioral and/or psychological abnormalities, often accompanied by physical symptoms. "H19 is possibly involved in the pathogenesis of psychiatric disorders through enhancement of neuron apoptosis." (PMID 33093650, 2020). "H19 might partake in the pathogenesis of psychiatric disorders by increasing neuronal apoptosis." (PMID 35410190, 2022).
hematologic malignancies (3 papers, 2023 to 2026). "The highest H19 expression level was found for gastrointestinal cancers, whereas the lowest levels were depicted for hematological malignant disorders." (PMID 41521159, 2026).
retinopathy (2 papers, 2020 to 2023). "The present study is the first to demonstrate dysregulation of H19 and GAS5 circulating RNAs in diabetic patients with and without retinopathy compared to controls in a population from the Middle East region." (PMID 31999937, 2020).
bacterial infection (1 paper, 2021). "We also discuss the involvement of Paneth cell dysfunction in altered susceptibility of the intestinal epithelium to chronic inflammation and bacterial infection following disrupted expression of HuR and H19." (PMID 34440876, 2021).
brain disorder (1 paper, 2022). A disease affecting the brain or part of the brain. "Previous studies have demonstrated that numerous lncRNAs are associated with various brain disorders, including GBM, such as TP73-AS1, H19, HOTAIR, and LINC00152." (PMID 35313638, 2022).
colon polyps (1 paper, 2023). "Patients with colon polyps did not present different H19 expressions." (PMID 37189829, 2023).
inflammation (1 paper, 2020). Aberrant reaction of the microcirculation characterized by movement of fluid and leukocytes from the blood into extravascular tissues. "H19 knock out (H19−/−) mice here were used to elucidate the roles of H19 in bleomycin-induced pulmonary inflammation and fibrosis." (PMID 33138822, 2020).
skeletal diseases (1 paper, 2019). "Although we have preliminarily explored the molecular mechanism of H19 regulating the matrix mineralization of osteoblasts in vitro, further in vivo experiments are needed to verify the feasibility of H19 as a potential therapeutic target for skeletal diseases in future studies." (PMID 31718549, 2019).
H19 also shares sentences with these, for which no sentence is quoted: acute myocardial infarction (7 papers); primary sclerosing cholangitis (5); idiopathic pulmonary fibrosis (4); liver (4); pulmonary hypertension (4); asthenozoospermia (3); colorectal adenocarcinoma (3); germ cell tumor (3); hyperlipidemia (3); nonalcoholic steatohepatitis (3); prediabetes (3); uterine fibroids (3); acute pancreatitis (2); alveolar rhabdomyosarcoma (2); benign tumors (2); childhood cancers (2); chronic myeloid leukemia (2); COVID-19 (2); developmental delay (2); embryonic rhabdomyosarcoma (2); endocrine disorder (2); essential thrombocythemia (2); genetic diseases (2); growth disorder (2); hematological tumors (2); Impaired glucose tolerance (2); irritable bowel syndrome (2); kidney stone (2); Li-Fraumeni syndrome (2); liver cirrhosis (2).
A further 113 diseases each share a sentence with H19 in 2 papers or fewer.